EGFR (epidermal growth factor receptor)
Diseases named in the same sentence as EGFR in open-access papers (continued):
Sharing a sentence is not in itself a finding about the gene and the disease.
tumor (continued). "Likewise, SKLB261 (multikinase inhibitor of EGFR, SRC, and VEGFR2) potently suppressed the proliferation and invasion of human PDAC cells, restored chemo-sensitivity, and extended the survival of tumor-bearing mice." (PMID 37120696, 2023). "Therefore, mutant EGFR-driven NSCLC has a unique immunosuppressive microenvironment, and EGFR activation promotes the expression of VEGF, which is expected to result in tumor angiogenesis." (PMID 37915579, 2023). "EGFR signaling can increase the expression of PKM2, which is extensively reviewed in cancer cells to promote tumor growth and might also contribute to the proliferative phenotype of injured PTECs." (PMID 36373978, 2023). "Everolimus was used as a second-line treatment in a patient with an EGFR mutation who had failed to respond to EGFR-TKI and had tumor regression." (PMID 36902280, 2023). "In particular, recurrent EGFR-amplified tumours showed increased expression of ZIC2, which is involved in increased cell proliferation, and increased expression of TFF1, which is involved in tumour cell migration." (PMID 36765632, 2023). "Additional clinical benefits may be conferred by the dual blockade of the EGFR and VEGF pathways that critical to tumor growth, metastasis and angiogenesis." (PMID 37635242, 2023). "Enrichment of EGFR expression to the basolateral domains of the tumor cells was only observed in our PTC samples with no change in the ERK activation pattern." (PMID 37114127, 2023). "AREG, one of the seven ligands that bind and activate EGFR, can promote the differentiation of T cells into Tregs in the tumor microenvironment, and targeting AREG in the tumor microenvironment may inhibit tumor invasion and immunosuppression." (PMID 37538176, 2023). "Next, we focused on the anti-tumor effects of GFP-Bro40 on EGFR TKI-resistant H1975 cells and used gefitinib as a negative control." (PMID 37821451, 2023). "Most patients who received first‐ or second‐generation EGFR‐TKI did not have sufficient tumor specimens for further immunohistochemistry." (PMID 37605832, 2023). "EGFR and ESR1 are confirmed as tumor drivers and drug targeting factors in ccRCC." (PMID 37542141, 2023). "Furthermore, the impact of different tumor suppressors on tumor number varied across oncogenic KRAS, BRAF, and EGFR contexts." (PMID 37828026, 2023). "Conversely, three patients did not have the EGFR amplification detected in the primary tumour but were found to have the EGFR amplification at the time of recurrence." (PMID 36765632, 2023). "Consistent with this consideration, in a study performed on HNSCC cell lines and tumor specimens it was observed that EGFR expression levels were not correlated with EGFR activity, evaluated via its phosphorylation status at multiple tyrosine residues." (PMID 36817764, 2023). "In addition to inhibition of EGFR signaling, the anti-PD1×EGFR bsAb triggers ADCC in tumor cells and leads to tumor shrinkage in xenografted and syngeneic CRC models." (PMID 36971124, 2023). "Taken together, our study shows that the anti-tumor effect of morin/Dox co-treatment is due to the suppression of FOXM1 and attenuation of EGFR/STAT3 signaling pathways in MDA-MB-231 TNBC cells, which suggests that morin offers a means of improving therapeutic efficacy in TNBC patients." (PMID 37242455, 2023). "EGFR and MET pathways are required for tumor cell proliferation and growth." (PMID 36979929, 2023). "EGFR was significantly lower in non-tumorous (histologically normal) tissue and tumours compared with healthy controls, and in tumours vs matching non-tumorous liver tissue from the same patients." (PMID 36890818, 2023). "EGFR signaling in cancer cells could promote N-glycosylation of SCAP by increasing glucose uptake and enhance tumor progression." (PMID 37938654, 2023).
tumor (continued). "Lastly, they observed significant differences in survival for patients with EGFR mutations compared to EGFR-WT (wild type) and EGFR pan-negative tumours, as well as ALK rearranged versus WT and ALK pan-negative tumours." (PMID 37686122, 2023). "Compound 5i significantly up-regulated the expressions of p-Akt, which were translated by tumor suppress genes, and the levels of p-EGFR and Akt remained unchanged regardless of treatment with 5i or gefitinib at 10 μM." (PMID 37110525, 2023). "Aberrant EGFR signaling pathways in GBM contribute to tumor progression by directly promoting tumor cell proliferation and survival, as well as establishing an immunosuppressive TME that allows for tumor immune escape." (PMID 37601668, 2023). "In a previous study, the dual inhibition of cyclooxygenase-2 (COX-2) and EGFR by melafolone led to the downregulation of PD-L1, transforming growth factor beta (TGF-β), VEGF, and the PI3K/AKT pathway, which decreased tumor cell proliferation and enhanced the proliferation of CD8+ T cells." (PMID 37444616, 2023). "HGF, MET-amplification and EGFR-T790M upregulate PD-L1 expression in NSCLC through different mechanisms, attenuating lymphocyte activation and cytotoxicity in vitro and in vivo, and promoting immune escape of tumor cells." (PMID 37089959, 2023). "Hence, by targeting EGFR-MET cross-talk inhibition with BS, we hold promise for combating tumor progression and metastasis." (PMID 37631372, 2023). "The tumor cell labelling efficiency of B10, B11, iNF-B11, B10-iNF and the bispecific construct B10–B11 was evaluated on the EGFR and PDL1 positive tumor cell lines MDA-MB-231 and MNNG-HOS, as well as on the PDL1+/CHO cell line engineered to overexpress PDL1 stably." (PMID 37189383, 2023). "While EGFR-TKI can reduce tumor burden, it cannot completely eradicate the tumor." (PMID 37046679, 2023). "We showed key differences in gene expression between primary and recurrent tumours and demonstrated that EGFR-amplified and non-amplified tumours both displayed increased EGFR pathway activity in the setting of recurrence." (PMID 36765632, 2023). "EGFR does not typically retort to ligand stimuli in the M phase of the cell cycle; overexpression of the receptor detected in the tumor disturbs this cell cycle-dependent negative regulation." (PMID 38090376, 2023). "There was a significant correlation between EGFR expression and age of patients (P=0.035), histological types (P=0.018) but not with tumor size (P=0.108)." (PMID 38974258, 2023). "As the EGFR is overexpressed in mesenchymal TNBC, which correlates with poor prognosis, it represents a potential tumor biomarker and target for personalized tumor therapy." (PMID 37048151, 2023). "For example, EGFR mutant organoids were sensitive to EGFR inhibitors, while NF1-mutant organoids with disrupted RAS/RAF/MEK signaling presented sensitivity to MEK inhibitors indicated by reduced tumor cell proliferation." (PMID 38596241, 2023). "LINC00969-mediated regulation of TKI resistance could enrich the knowledge of tumour resistance, and LINC00969 has great prospects as be a prognostic indicator and a potential therapeutic target for overcoming EGFR-TKI resistance in NSCLC." (PMID 37156816, 2023). "The median percentage of viable tumor in resected patients without known tumor EGFR/ALK alterations was 51% (range 0–95.5%) in the Nivo+CT arm (n = 17) compared with 2.8% (range 0–94.4%) in the Ipi+Nivo+CT arm (n = 14)." (PMID 36928818, 2023). "Some Mabs target EGFR, HER2, IGF‐1R, HGF, and VEGF; others may be checkpoint inhibitors (including Mabs to PD‐1, CTLA4, and NKG2A) or tumor‐targeting Mabs such as U36 and Mab E48." (PMID 37042307, 2023). "Nimotuzumab has been approved in several countries for clinical treatment of various tumor types due to the absence of severe adverse effects, which is in contrast to numerous other drugs that target EGFR." (PMID 37762316, 2023).
tumor (continued). "TAMs mediate EGFR-TKIs resistance in NSCLC through various mechanisms, including activation of bypass pathways, inhibition of T cell activity, M2-like polarization, and regulation of tumor cell phenotypes." (PMID 37649478, 2023). "Several critical signaling pathways, such as phosphatidylinositol 3-kinase (PI3K)/protein kinase B (PKB, Akt)/mammalian target of rapamycin (mTOR), epidermal growth factor receptor (EGFR), and Ras, can regulate SREBP1/2 activation to mediate tumor growth and progression." (PMID 37568579, 2023). "And in a study on patients with GBM surviving more than 1 year, the expression of EGFR vIII was found to be an independent negative prognostic marker of survival, indicating it as a key potential target for anti-tumor immunotherapy." (PMID 37046332, 2023). "Another reason for higher IO efficacy in BRAF-mutant NSCLC, as opposed to EGFR or ALK, is the higher tumor mutational burden (TMB) and more frequent smoking status, as almost half of the BRAF-mutant NSCLC patients are found to be smokers." (PMID 37629023, 2023). "Another critical aspect of current research in SCCA is the personalization of CRT and immunotherapies based on molecular characterization and biomarkers such as the programmed death-ligand 1 (PD-L1), epidermal growth factor receptor (EGFR) and circulating tumor DNA." (PMID 38063578, 2023). "We found MPR and pCR rates of 41.2% and 23.5%, respectively, and a 12-month and 24-month EFS of 100% and 71%, respectively, in patients without known tumor EGFR/ALK alterations." (PMID 36928818, 2023). "The antitumour efficacy of bispecific antibodies plus talazoparib was not improved in the tumours that were insensitive to EGFR blockade, corresponding to the high expression of VIM and FN1 genes and relatively low expression of CDH1 and CLDN7 genes." (PMID 37441599, 2023). "To this end, we generated MDA-MB-231 tumor xenograft in mice and performed confocal microscopy analysis of tumor tissue sections upon immunofluorescence staining with FITC-peptides (green signal) or anti-EGFR (red signal)." (PMID 37048151, 2023). "In patients without known tumor EGFR/ALK alterations, MPR rates were 41.2% (7/17) and 62.5% (10/16) in the Nivo+CT and Ipi+Nivo+CT groups, respectively." (PMID 36928818, 2023). "We analyzed tumor samples submitted to Caris Life Sciences (n=64,354), as well as the TCGA (n=10,967), MSK IMPACT (n=10,945) and AACR GENIE (n=96,324) databases for evidence of EGFR, ERBB2 and ERBB4 gene fusions." (PMID 37168365, 2023). "Arsenic significantly enhanced the expression of LC3 in NSCLC tumor cells (p < 0.001, p < 0.01), but gefitinib had a weak effect on the expression of LC3 and P62 in tumor cells from patients harboring various EGFR genotypes." (PMID 37371816, 2023). "Our findings suggest that under the inhibitory effect of an EGFR TKI, HGF-mediated PIP3 activation may bypass EGFR-mediated PIP3 activation, an observation further supported by elevated HGF expression in tumors with higher tumor-stroma interactions." (PMID 36647832, 2023). "Despite plenty of studies investigating the effectiveness of targeted therapy, there were still no suitable biomarkers to predict the anti‐tumor activity of anti‐EGFR or anti‐VEGF/VEGFR agents." (PMID 38063316, 2023). "EGFR overexpression has been related to more aggressive tumor phenotypes, poor patient prognosis, and lack of response to antitumor therapies." (PMID 38026933, 2023). "In contrast, no patients had tumor response when the EGFR GCN or chromosome 7 polysomy was less than this value." (PMID 37974093, 2023). "Since it was confirmed that the activity of EGFR can be enhanced by GPNMB, we further investigated whether CCN3-induced metastasis and tumor progression were mediated by GPNMB-induced mechanisms." (PMID 36737605, 2023). "Furthermore, attenuation in TGF-β-induced EGFR transactivation and activation of the PI3K/AKT pathway leads to the formation of unwanted growth of cells called tumor." (PMID 37053209, 2023).
tumor (continued). "We note, however, that because of absent data on tumor sidedness, we were unable to determine the appropriateness of the treatment received with respect to EGFR inhibitors." (PMID 36656585, 2023). "With regard to MSN-AP, their applications also have limitations due to the nonhomogeneous expression of EGFR on tumor cells." (PMID 36768288, 2023). "Epidermal growth factor (EGF) and EGFR are expressed in functioning and non-functioning PitNETs, with higher expression in more aggressive tumor subtypes." (PMID 37446128, 2023). "In addition, macrophages showed an increase in TrisoMab-mediated tumour cell ADCP and ADCC compared to EGFR-specific IgG and IgA." (PMID 36817447, 2023). "Of the EGFR non-amplified tumours, three switched from proneural to classical, three switched from classical to mesenchymal, and two switched from mesenchymal to classical." (PMID 36765632, 2023). "Mechanistically, the EGFR-TKIs inhibit the growth of sensitive mutant tumor cells rather than eradicating potential micrometastases of EGFR wild-type cancer cells." (PMID 37528390, 2023). "In comparing paired primary and recurrent tumour samples, EGFR-amplified tumours displayed a unique set of differentially expressed genes when contrasted with EGFR non-amplified tumours." (PMID 36765632, 2023). "Similarly to the EGFR inhibitors, the two selected MEK inhibitors (selumetinib and trametinib), which are included in a clinical-phase study on several tumor types, were also tested for their effects on cell viability." (PMID 36769112, 2023). "Moreover, the Fc-silent format of CD27xEGFR enables tumor-localized binding and crosslinking of CD27 only at EGFR+ tumor sites, potentially enhancing its specificity and safety profile." (PMID 37545491, 2023). "Fourth, many confounding factors such as the different efficacies of osimertinib vs other EGFR TKIs, the site of metastases, tumor burden, and performance status have not been taken into consideration." (PMID 36810562, 2023). "Only one of 301 breast lesions tested by the MAPP was positive for EGFRvIII, and this tumor did not exhibit EGFR amplification." (PMID 38201434, 2023). "These tumor cells rely on the EGFR protein–mediated, TKI-insensitive EGFR signaling, but not EGFR kinase activity, for survival and are insensitive to EGFR kinase inhibitors." (PMID 37178919, 2023). "Apart from blocking EGFR signaling, it also abrogates tumor growth by activating natural killer cells via antibody-dependent cellular cytotoxicity (ADCC), and also induces adaptive immunity via tumor antigen-specific T cells." (PMID 37623652, 2023). "In this paper, we present the In Silico EGFR-mutant LUAD (ISELA) model that links LUAD patients’ individual characteristics, including tumor genetic heterogeneity, to tumor size evolution and tumor progression over time under first generation EGFR tyrosine kinase inhibitor gefitinib." (PMID 37524705, 2023). "The human epidermal growth factor receptor 2 (HER2) is a member of the epidermal growth factor receptor (EGFR) family of tyrosine kinase receptors and plays a crucial role in cell proliferation and differentiation, inhibition of apoptosis and tumor progression." (PMID 37637599, 2023). "The acquired resistance of EGFR-TKI always develops after a dramatic initial response followed by a stable minimal residual disease (MRD), or dormant state, with subsequent a drug-resistant tumor 49,50." (PMID 37215986, 2023). "From an overall tumor-feature perspective, our MIL models tended to predict lepidic and papillary patterns as EGFR mutant and any mucinous characteristic (architecture and cytology) as EGFR wild-type." (PMID 36927889, 2023). "Data from the CRYSTAL and TAILOR studies also confirm that adding cetuximab to chemotherapy improved the survival benefit of first-line treatment for patients with RAS wt mCRC, irrespective of tumor EGFR status." (PMID 37974093, 2023).
tumor (continued). "Further, patients likely to be nonbenefitting from EGFR TKI therapy had increased tumor-stroma interactions and showed evidence that the crosstalk between tumor cells and fibroblasts was a source of EGFR TKI resistance." (PMID 36647832, 2023). "They showed that the combination of these drugs significantly induces apoptosis and reduces the phosphorylation of EGFR, PI3K, and Akt, which may contribute to the inhibition of tumor growth." (PMID 37190301, 2023). "In addition, we co-transfected A549 and NCI-H23 cells with EGFR overexpressing vector and LAMC2 siRNA to assess their potential counteracting effects on tumor cell activity, proliferation, cell cycle, and apoptosis." (PMID 37542131, 2023). "The isolated peripheral T cells can be genetically engineered to target several known tumor antigens of HNSCC, including, EGFR, MAGE-A4, MUC1, CD 70, and HER2, and the ACT with these agents has demonstrated a durable clinical response in early clinical studies." (PMID 36992219, 2023). "Additionally, a Phase I clinical trial that utilises CAR-T cell therapy to target EGFR- and CD19-positive tumours to treat children and young adults with recurrent/refractory solid tumours is ongoing (NCT03618381)." (PMID 37681936, 2023). "Tumour zcc446 had a different molecular profile with aneuploid genome, lack of AVCR1 or EGFR mutations and negative EZHIP IHC." (PMID 36882456, 2023). "Indeed, knockout or small hairpin RNA (shRNA)-mediated knockdown of PDCD1 enhanced the anti-tumor efficacy of C-type lectin-like molecule-1 (CLL-1)-, mesothelin-, epidermal growth factor receptor (EGFR)-, CD19-, and Glypican-3 (GPC3)- CAR-Ts." (PMID 37046597, 2023). "In the subgroup of FIGO II-IV tumor tissue samples with available adjacent negative tissue controls (n = 26), both EGFR and p-mTOR (r = −0.450, p < 0.001) as well as p-mTOR and ER (r = 0.426, p < 0.001) expression demonstrated significant correlations." (PMID 37623437, 2023). "NANOG+ cells exhibited stem-like, metastatic, anti-apoptotic properties, and resistance to multi-modal therapies, such as chemo-, radio-, and immunotherapy, by hyperactivation of the EGFR-AKT pathway, indicating the important role of NANOG signaling in these refractory phenotypes of tumor cells." (PMID 37165076, 2023). "Indeed, co-immunoprecipitation (Co-IP) of SPINK1 and EGFR in HCC cells confirmed their binding; while multiplex immunostaining demonstrated their colocalization in human HCC tumor samples." (PMID 38030644, 2023). "Interestingly, the overall tumor suppressive landscapes of BRAF- and EGFR-driven lung tumors were dramatically different from each other as well as from oncogenic KRAS-driven tumors." (PMID 37828026, 2023). "The Idylla EGFR Assay does not specify the minimum tissue area for loading, but only requires the tumor cell proportion and the maximum tissue area for loading." (PMID 37064089, 2023). "Additionally, it has been revealed that EGFR and HER2 activation are related to STAT3 activation, which also encourages tumor survival and development." (PMID 37415164, 2023). "Alternatively, approaches targeting TAMs combined with immunotherapy targeting EGFR or VEGFR and/or HIF-1/2 may warrant preclinical and clinical testing and inhibit tumor expansion." (PMID 38033495, 2023). "As our data demonstrated, VEGF antibody therapy had a better tumor response than EGFR antibody therapy independent of RAS status." (PMID 37296862, 2023). "Since EGFR per se acts as a major cargo of EVs and contributes to tumor metastasis, angiogenesis, and TKI resistance, exosomal delivery of JMJD5 may represent a putative strategy for EGFR-targeted therapy of NSCLC." (PMID 37813845, 2023).